TNF (tumor necrosis factor)
Diseases named in the same sentence as TNF in open-access papers (continued):
Sharing a sentence is not in itself a finding about the gene and the disease.
melanoma (continued). "Inflammatory signals such as TNF and MMP-2 activity are key intrinsic players to determine melanoma cells aggressiveness suggesting new venue sin the identification of novel molecular targets with potential therapeutic relevance." (PMID 30591049, 2018). "In this study, we tested the feasibility and effectiveness of in situ vaccination with TNFα and IL-12 by concomitant GET in murine melanoma tumors." (PMID 29468364, 2018). "This is in-line with our finding that melanoma-conditioned TAMs displayed M2-like phenotype, including increased CD163 protein expression and TNF-α low, IL-1β low, TGF-β high and IL-10 high phenotype." (PMID 30459241, 2018). "In the current study the effect of Zymosan A derived from Saccharomyces cerevisiae on serum TNF-α expression and on TLR2 and 4 genes expression in peritoneal macrophages and on melanoma growth progression was investigated." (PMID 29588627, 2018). "TNF potently stimulated TIM-3 expression on CD8+ TILs and this was enhanced upon autologous co-culture with melanoma cells." (PMID 29273790, 2017). "We next sought to evaluate the effect of exogenous TNF on CD8+ TILs purified from human melanoma samples under basal conditions (i.e., IL-2 alone) or after autologous re-stimulation with melanoma cells for 48 h." (PMID 29273790, 2017). "TNF expression positively correlates with expression of PD-L1 and TIM-3 in human melanoma specimens." (PMID 29273790, 2017). "Only when we co-stimulated endothelial cells with 50ng/mL TNF-α and 20ng/mL IFN-γ for 20 hours adhesion of melanoma cells was significantly increased." (PMID 28253287, 2017). "We show here that TNF blockade leads to an increased content of CD8+ TILs, which is predictive of the response to anti-PD-1 in melanoma patients." (PMID 29273790, 2017). "TNF-induced CCL20 is conferred by a region between -111 and -77, which contains a κB-like site in G-361 human melanoma cells." (PMID 27723802, 2016). "TNF targets the quiescent/slow-cycling stem cells and promotes PI3K/AKT-driven expansion in melanoma by preventing their asymmetrical self-renewal." (PMID 26992212, 2016). "Previous work carried out in our lab combining GLV-1h68 (oncolytic vaccinia virus) and RT showed a synergistic effect in BRAF mutant melanoma that is mediated through JNK and TNFα signalling." (PMID 27384486, 2016). "The inhibition of TNFα/NF-κB pathway and CD271 silencing restore the BRAFi sensitivity of resistant melanoma cells." (PMID 27462428, 2015). "It has been shown that immune cells are able to secrete TNFα, which in turn upregulates CD271 in melanoma cells." (PMID 27462428, 2015). "FKBP51 knockdown in A375 melanoma cells, using three different shRNAs, profoundly reduced the kinase activity of IKK after stimulation with TNFα (upper)." (PMID 26101251, 2015). "Taken together, these results imply that HIFU suppresses the expression of miR-134 in melanoma cells to enhance CD86 expression, which enhances anti-tumor immunity by triggering IFN-γ and TNF-α secretion from lymphocytes." (PMID 26485753, 2015). "We tested a battery of cytokines, including IL-8, TNFα, MIP1, MCP1, IL-4, and IL-17a, in pretreatment (basal) serum samples of melanoma patients who responded to TIL treatment (n = 8) as compared with patients who failed to respond (n = 8)." (PMID 26688824, 2015). "α-Catulin knockdown also decreased NF-ĸB activity after TNFα-, LPS-, HGF- and Serum (10% FCS) activation in Melanoma 7 cells, which is consistent with our previous finding that α-catulin is central for mediating NF-ĸB activation." (PMID 25793618, 2015). "Our recent findings demonstrate that TNF-R1-dependent TNF signaling impairs CD8+ TIL content and likely constitutes a potent immune checkpoint in melanoma, facilitating melanoma progression." (PMID 26622939, 2015). "As shown with melanoma, mRNA levels of IFN-γ, TNF-α, IL-2, IL-18, IL-10, and VEGF-A were significantly decreased in kCYC mice compared with WT mice in draining LNs on day 14 (p < 0.05, respectively)." (PMID 26098776, 2015).
melanoma (continued). "TNF significantly stimulated tumor-like sphere formation in both cell lines, indicating that the TNF effect is BRAFV600E-independent and confirming that TNF expands the melanoma SC pool." (PMID 25223735, 2014). "We conclude that pro-inflammatory TNF targets the quiescent/slow-cycling melanoma SC compartment and promotes PI3K/AKT-driven expansion of melanoma SCs most likely by preventing their asymmetrical self-renewal." (PMID 25223735, 2014). "Inclusion of LBH589 together with adoptive T cell transfer induced significant regression of established B16 melanoma tumors while generating a systemic proinflammatory cytokine milieu, illustrated by the sustained release of IFN-γ and TNF." (PMID 25054063, 2014). "In this study, we investigated the effect of UV-radiation on p38 MAPK (mitogen-activated protein kinase), JNK and NFκB pathways to determine which plays a major role in stimulating TNFα secretion in human HEM (melanocytes) and MM96L (melanoma) cells." (PMID 23965971, 2013). "Studies on human endothelial cells and other melanomas report that HLA-E can be shed upon treatment with IFN-γ, IL-1β or TNF-α." (PMID 24236107, 2013). "Both the EP4 antagonist and the p38 MAPK inhibitor reduced MCP-1 production in melanoma cells, and abrogated the increased MCP-1 secretion induced by TNF-α or exogenous PGE2." (PMID 23420676, 2013). "In this study, we compared the effects of UV radiation on the activation of the p38, JNK and NFκB pathways, as well as TNFα secretion in primary human epidermal melanocytes (HEM) and a melanoma cell line (MM96L)." (PMID 23965971, 2013). "Infused T cells were tested for production of different cytokines (TNF-α and IFN-γ) when co-cultured with autologous melanoma cell lines (2 patients) or a panel of HLA-A matched allogeneic cell lines (4 patients)." (PMID 22909342, 2012). "TCR T cells killed and produced IFNγ and TNFα upon coculture not only with MC2 peptide-pulsed HLA-A2-positive target cells but also native MC2-positive, HLA-A2-positive melanoma cells." (PMID 22400038, 2012). "Serum cytokine levels (including IL-1α, IL-1β, IL-2, IL-6, IL-10, IL-12, TNF-α, IFN-γ and IFN-α) were lower in A375 melanoma bearing mice treated with G3139 + VRP + ACV + PAC.PBP + DNR + X rays than in controls treated with physiological saline." (PMID 22233801, 2012). "Another NSAID, sodium salicylate, both inhibited TNF-α-stimulated NF-kB activation and downregulated ICAM-1 expression in melanoma cells." (PMID 24212647, 2011). "We demonstrate the contribution of VEGF-induced tumor COX-2 to the regulation of adhesion- and proliferation-stimulating effects of TNFα, from endotoxin-activated bone marrow stromal cells, on VLA-4-expressing melanoma cells." (PMID 21867538, 2011). "Isolated limb perfusion with TNF and melphalan followed by low-dose IFN-α systemic therapy improved the progression-free survival in a pilot study of melanoma patients with in-transit metastases." (PMID 24281094, 2010). "Chemokine expression by the D5 melanoma following co-culture with T cells, IFN-γ or TNF-α was determined by RT-PCR and ELISA." (PMID 18001476, 2007). "Melanoma cells release a number of osteoclastogenic factors including TGF-β, IL-6, M-CSF, GM-CSF and TNF-α; these cells also upregulate osteoblast expression of factors known to stimulate RANKL-dependent osteoclastogenesis." (PMID 16641914, 2006). "Tumor necrosis factor-α and other cytokines/growth factors that induce osteoclast formation by a RANKL-independent mechanism, are known to be produced by melanoma cells." (PMID 16641914, 2006). "A higher percentage of γδ+ T cells producing TNF-α was found in old healthy donors, whereas a reduced number of TNF-α-producing γδ+ T cells was present in melanoma patients independently by age." (PMID 15686597, 2005).
melanoma (continued). "Since it has been demonstrated that activated γδ T cells produce TNF-α and IFN-γ, we studied the intracellular production of these cytokines in one-day stimulated γδ T cells from healthy subjects and melanoma patients." (PMID 15686597, 2005). "Mice were treated i.p. with either PBS or anti-TNF monoclonal antibodies (CV1q), and then B16F10 melanoma cells were injected into the tail vein." (PMID 15026813, 2004). "The aim of this study was to investigate the effect of the proinflammatory cytokine TNF-α and the anti-inflammatory peptide α-MSH on melanoma cell migration." (PMID 15054471, 2004). "Having shown that blocking TNF can have an effect on metastasis, we examined the effect of immunisation with TNF autovaccine in the B16F10 melanoma model in three independent experiments." (PMID 15026813, 2004). "The induction of high levels of anti-TNF antibodies reduced the number of metastases reaching and establishing themselves in the lungs as well as their size in the B16F10 murine melanoma model when compared to mice immunised with PBS in CFA." (PMID 15026813, 2004). "In this study, we examined the ability of TNF autovaccination to generate anti-TNF antibody titres and block metastasis in the murine B16F10 melanoma model." (PMID 15026813, 2004). "We have recently shown that while the proinflammatory cytokine TNF-α upregulates integrin (α3, α4, β1) expression in HBL melanoma cells, treatment with α-MSH results in a reduction in integrin expression." (PMID 14612916, 2003). "Isolated limb perfusion (ILP) with tumour necrosis factor alpha (TNF-alpha) and melphalan has shown impressive results in patients with irresectable soft tissue sarcomas and stage III melanoma of the extremities." (PMID 8980389, 1996). "In vitro, BCNU alone was cytotoxic to murine B16 melanoma cells, and at all concentrations of BCNU this toxicity was increased by the addition of TNF." (PMID 2245169, 1990). "In melanoma cells, SK1 and its product S1P are key components of TNF signaling." (PMID 41596686, 2026). "Two complementary inflammation models were used to assess immunomodulatory potential, (i) LPS-stimulated macrophages and (ii) TNF-α/IFN-γ-stimulated immortalized HaCaT keratinocytes, while cytotoxicity and selectivity were tested on human HaCaT keratinocytes and melanoma cell lines (A375, HTB140)." (PMID 41900067, 2026). "In cultured murine melanoma B16F1 cells and THP‐1 cells, methanolic extracts of fenugreek seed inhibited the yield of phorbol‐12‐myristate‐13‐acetate‐induced inflammatory cytokines like tumor necrosis factor (TNF)‐a." (PMID 40918167, 2025). "Despite the lack of change in TNF-α levels, we can conclude that melanoma inhibits M1 polarization based on the CD68 expression results." (PMID 39995996, 2025). "Adipocytes in obese patients with melanoma release high amounts of pro-inflammatory cytokines and growth factors (IL-6, IL-32 or TNF-α) and molecules involved in the angiogenesis enhancement (OPN—osteopontin, chemerin, apelin and PAI-1) that modulate melanoma proliferation." (PMID 40136652, 2025). "Similar results have been reported in another non-osteogenic environment with a higher presence of TNFα leading to the upregulation of TNFRSF11B in melanoma cells, which in that instance promoted tumor cell survival." (PMID 40665262, 2025). "Systematic reviews in IBD, rheumatoid arthritis, and psoriasis populations similarly do not support a significant link between anti-TNF therapy and melanoma." (PMID 41228267, 2025). "In addition, we investigated several tumor progression proteins that are frequently assessed in the clinical evaluation of melanoma, such as LDH, S100, IL-6, and TNF-α." (PMID 40564098, 2025). "In the melanoma dataset, five pathways were consistently identified as spatially deregulated by all three methods: Cytosolic DNA sensing, NF-kappa B signaling, PPAR signaling, TNF signaling, and Toll-like receptor signaling." (PMID 40827204, 2025).
melanoma (continued). "Additionally, RT-PCR analysis showed that Jurkat cells co-cultured with Vin-treated melanoma cells exhibited significantly higher mRNA levels of IFNγ, GZMB, IL-2, and TNFα in the activated state." (PMID 40866941, 2025). "In addition, melanoma subpopulations were detected as receivers of immune signals such as GAS and TNF." (PMID 40866912, 2025). "Conversely, tumour growth can be suppressed by other cytokines and growth factors such as tumour necrosis factor-alpha (TNF-α), TGF-β, interferon-alpha, bioactive monoamines, and through the antiproliferative effects of tryptase, which have been documented in melanoma." (PMID 40981193, 2025). "Furthermore, increased serum TNF-α levels and the correlation of RIPK4 with NF-κB were revealed in melanoma patients." (PMID 38656555, 2024). "As expected, TNF decreased the gene expression of MITF and its target genes MLANA, DCT and TYR, and, conversely, increased the expression of the stemness factor NGFR in 451Lu melanoma cells." (PMID 39136013, 2024). "Finally, in one of our clinical studies, we evaluated the safety and tolerability of combining an anti-TNF agent, either infliximab or certolizumab, with anti-CTLA-4 (ipilimumab) and anti-PD-1 (nivolumab) antibodies in advanced melanoma patients." (PMID 39136013, 2024). "Validation of the pro-inflammatory genes including IL6, TNF, and IL1B revealed a significant increase in their expression in macrophages cultured with melanosomes derived from melanoma cells, keratinocytes, or fibroblasts as compared to naïve macrophages (Fig. EV4A)." (PMID 38719996, 2024). "In melanoma-bearing mouse models, butyrate supplementation with anti-PD-1 therapy significantly reduced tumor volume and increased the percentage of IFN-γ+ and tumor necrosis factor (TNF)-α+ cells among tumor infiltrating CD4+ and CD8+ T cells." (PMID 39840031, 2024). "Collectively, our data indicate that AC silencing, mimics, at least in part, TNF-induced melanoma dedifferentiation, also suggesting that AC is not the only player in this mechanism." (PMID 39136013, 2024). "The impact of TNF on melanoma dedifferentiation was not restricted to the primary melanoma cell line WM35." (PMID 39136013, 2024). "TNFα is also known to impede the infiltration of tumors by CD8+ lymphocytes, trigger activation-induced cell death of CD8+ T cells, and inhibit the responses of cytotoxic CD8+ T cells, thereby fostering immune evasion and relapse in melanoma." (PMID 38610706, 2024). "Additionally, co-delivered nanovaccines increase the generation of pro-inflammatory cytokines by DCs, such as IFN-β, TNF-α, CXCL-9, and CXCL-10, which promote the proliferation and recruitment of antigen-specific CD8+ T cells in melanoma TME." (PMID 38185685, 2024). "Five genes (CXCL10, TNF, PIK3CD, PIK3R2, and CXCL1) of the TNF signalling pathway and seven genes (CXCL9, GDF15, BMP7, TNFRSF15, CXCL10, TNF, and CXCL1) of the cytokine–cytokine receptor pathway were commonly upregulated in melanoma cells." (PMID 39496484, 2024). "The alterations of ceramide metabolism upon TNF treatment in melanoma cells do not seem to be restricted to the AC inhibition." (PMID 39136013, 2024). "To determine a mechanism by which TTR macrophages could drive resistance formation in melanoma, we first examined factors known to mediate this process, such as VEGF31 and TNFα." (PMID 38942020, 2024). "In EVs derived from melanoma, specific miRNAs, including miR-3187-3p, miR-498, miR-122, miR-149, and miR-181a/b, were found to downregulate T cell receptor (TCR) signaling and the secretion of tumor necrosis factor-α (TNF-α) in CD8+ T cells." (PMID 38562940, 2024). "However, IRF7 knockdown with small interfering RNA (siRNA) significantly inhibited these inflammatory factors (IL‐1β, TNF‐α, IFN‐α, and IFN‐β), CD80 and CD86 in macrophages co‐cultured with irradiated melanoma cells." (PMID 38286661, 2024).
melanoma (continued). "Moreover, we found significant enrichment of pro-inflammatory IL6, TNF, and IFNγ gene sets in macrophages that had taken up melanosomes secreted by MNT1 melanoma cells and in those that had taken up melanosomes from either keratinocytes or fibroblasts." (PMID 38719996, 2024). "Tyciakova observed that TNF-α overexpression is accompanied by a significant upregulation of the proinflammatory cytokine IL-6 gene in A375 melanoma cells and proapoptotic ligand TRAIL gene in colorectal cancer cell HT29, both of which were mediated by TNF-α/TNFR1 signaling." (PMID 38656555, 2024). "Furthermore, in a mouse model of adoptive transfer of specific T cells, TNF was found to directly impact tumor cells and lead to the establishment of an epithelial-to-mesenchymal transition (EMT)-like process called melanoma dedifferentiation." (PMID 39136013, 2024). "In the context of melanoma, MDMs trigger glucocorticoid signaling that activates an array of checkpoint receptors including PD-1, Tim-3, LAG-3, and IL-10, and reduces levels of pro-inflammatory cytokines such as TNF-α, IL-2, and IFN-γ." (PMID 39068459, 2024). "In melanoma, TNF-α not only induces tumor metastasis ADDIN EN.CITE, but also inhibits CD8 T lymphocytes accumulation in the TME ADDIN EN.CITE, leading to further evaluation of a TNF-α blockade in pre-clinical models." (PMID 38520006, 2024). "We further showed that at this point, the melanomas were the dominant source of TNF-α rather than KCs surrounding the tumor area." (PMID 37043573, 2023). "In vitro experiments demonstrated that adenosine produced by melanoma could inhibit IFN-γ production by ILC1s, while TNFα secretion was poorly affected." (PMID 36765891, 2023). "Recent findings have indicated that melanoma cells displaying increased constitutive PDL-1 expression had a diverse transcriptomic profile characterized by de-differentiation and active tumor necrosis factor (TNF) and interferon (IFN) signaling pathways, potentially contributing to resistance." (PMID 38139110, 2023). "This speculation is confirmed at least by the properties of TA99-TNFα, an immunocytokine that consists of a TA99 scFv fragment (anti gp75 melanoma antigen) and TNF-α moieties." (PMID 36839658, 2023). "Intraperitoneal administration of andrographolide significantly inhibited the B16-F10 melanoma cell line-induced capillary formation in C57BL/6 mice and reduced the levels of pro-inflammatory cytokines, such as IL-1β, IL-6, TNF-α and GM-CSF, and serum NO level." (PMID 36768978, 2023). "The IRs of melanoma seem to be comparable across patients treated with newer drugs (IL-17 inhibitors, IL-23 inhibitors, JAK inhibitors), and they similarly correspond to the previously published findings concerning patients receiving TNF-α inhibitors." (PMID 38276003, 2023). "However, a recent in vivo study showed the effective, neutrophil-mediated killing of B16 melanoma cells when combining an IgG antibody targeting gp75 (a protein expressed on B16 melanoma cells), an CD40 antagonist and TNF." (PMID 37566060, 2023). "Recently, a clinical trial phase 1b was performed in patients with advanced melanoma with a combination of anti-PD-1, anti-CTLA-4, and anti-TNFα (certolizumab and infliximab), which revealed a clinical benefit in 66.7% of the patients on certolizumab and 50% in the infliximab cohort." (PMID 36981837, 2023). "Likewise, NR2F6 expression was unchanged in cultured human melanoma cells before and after IFN-γ or tumor necrosis factor–α (TNFα) treatment [fig." (PMID 37406115, 2023). "In particular, gene expression profiling of B16-F10 melanoma cells reveals that mangiferin selectively inhibits expression, among others, of IL6, TNF, IFNG, VEGFR2, MMP19 and FGF1 genes with consequent deregulation of angiogenesis, cell viability and metastatic processes." (PMID 36768978, 2023).